RIOX2 (ribosomal oxygenase 2)
Description:
Oxygenase that can act as both a histone lysine demethylase and a ribosomal histidine hydroxylase. Is involved in the demethylation of trimethylated 'Lys-9' on histone H3 (H3K9me3), leading to an increase in ribosomal RNA expression. Also catalyzes the hydroxylation of 60S ribosomal protein L27a on 'His-39'. May play an important role in cell growth and survival. May be involved in ribosome biogenesis, most likely during the assembly process of pre-ribosomal particles.
Synonyms: ROX; MDIG; MINA; MINA53; NO52; FLJ14393; JMJD10
Tractability: Small molecule: a structure with a bound ligand is known; it has a binding pocket of medium quality. PROTAC: ubiquitination databases record sites on it.
Target class: Enzyme; Oxidoreductase
Gene: Protein-coding gene on chromosome 3 (97,941,815 to 97,972,457, reverse strand). Ensembl gene ENSG00000170854.
Subcellular location: Nucleus; Nucleus, nucleolus
Subcellular location (Human Protein Atlas): Nucleoli; Nucleoplasm
Pathways (Reactome):
Chromatin organization: HDMs demethylate histones
Metabolism of proteins: Protein hydroxylation
Gene Ontology:
Molecular function: identical protein binding; peptidyl-histidine dioxygenase activity; protein binding; histone demethylase activity; histone H3K36 demethylase activity; histone H3K4 demethylase activity; transcription corepressor activity
Biological process: protein hydroxylation; chromatin remodeling; negative regulation of DNA-templated transcription
Cellular component: nucleolus; nucleoplasm; nucleus; cytosol; transcription regulator complex
Genetic constraint (gnomAD): Loss-of-function variants: 31 observed, 42.77 expected, observed/expected ratio (o/e) 0.72, 90% interval 0.54 to 0.98. The upper end of that interval is the gene's LOEUF score, 0.98, which puts it in group 4 of 6, group 1 being the genes least tolerant of losing a copy. Missense variants: 516 observed, 534.05 expected, observed/expected ratio (o/e) 0.97, 90% interval 0.9 to 1.04. Synonymous variants: 212 observed, 215.19 expected, observed/expected ratio (o/e) 0.99, 90% interval 0.88 to 1.1.
Homologues: Orthologues: chimpanzee RIOX2 (99% identical), macaque RIOX2 (98% identical), rabbit RIOX2 (90% identical), pig RIOX2 (87% identical), guinea pig RIOX2 (86% identical), dog RIOX2 (80% identical), rat Riox2 (80% identical), mouse Riox2 (77% identical), zebrafish riox2 (57% identical), tropical clawed frog riox2 (54% identical), Drosophila melanogaster NO66 (26% identical), Caenorhabditis elegans jmjc-1 (26% identical). Paralogues in human: RIOX1 (31% identical).
Diseases named in the same sentence as RIOX2 in open-access papers:
RIOX2 is named in the same sentence as 51 diseases in open-access papers, as found by Europe PMC text mining. Sharing a sentence is not in itself a finding about the gene and the disease. The quoted sentences say what the papers report.
lung carcinoma (8 papers, 2014 to 2023). "The expression and methylation characteristics of RIOX2 in lung cancer indicate its unique role in tumor progression, which affects the prognosis of patients." (PMID 34855761, 2021). "In a similar manner, from previous examples, the integration of cancer bioinformatics has led to the recent discovery of ribosomal oxygenase 2 (RIOX2) as a key oncogene in lung cancer, which also participates as a common factor in a variety of carcinogenic disturbances." (PMID 37489388, 2023). "Highly-expressed RIOX2 is associated with a lower overall survival rate in lung cancer patients, without lymph node metastasis or only with proximal lymph node metastasis but it does not predict that of patients with distant lymph node metastasis." (PMID 34855761, 2021). "However, the molecular mechanism of RIOX2 gene in the development of lung cancer may be helpful in improving lung cancer therapy." (PMID 34855761, 2021).
liver cancer (3 papers, 2017 to 2023). An epithelial or non-epithelial malignant neoplasm that arises from the liver. "In addition, RIOX2 expression was found to strongly correlate with ZNF143, which was previously shown to enhance RIOX2 gene expression in liver cancer cells." (PMID 36776320, 2023).
lung adenocarcinoma (2 papers, 2020 to 2021). A carcinoma that arises from the lung and is characterized by the presence of malignant glandular epithelial cells. "It was found that RIOX2 is highly expressed in lung adenocarcinoma (LUAD) and lung squamous cell carcinoma (LUSC) tissues, whose expression is negatively correlated with its methylation level." (PMID 34855761, 2021). "According to the analysis based on the databases, RIOX2 gene could not be considered as the independent prognostic biomarker in lung adenocarcinoma or squamous cell lung cancer." (PMID 34855761, 2021).
prostate carcinoma (1 paper, 2023). A carcinoma that arises from epithelial cells of the prostate gland. "Most significantly, the c-Myc target gene RIOX2 was upregulated and tightly associated with disease progression and patient survival outcomes, representing a novel prognostic factor in prostate cancer." (PMID 36776320, 2023). "COX regression analysis identified that the ribosomal oxygenase 2 (RIOX2) gene was the only one significantly associated with disease-specific survival outcomes in prostate cancer patients." (PMID 36776320, 2023). "RIOX2 upregulation was confirmed at the protein levels using immunohistochemical assays on prostate cancer tissue sections." (PMID 36776320, 2023). "We conducted a comprehensive transcriptomic analysis of 35 histone demethylases in prostate cancer and identified RIOX2 as a potent prognostic factor for disease-specific survival in prostate cancers." (PMID 36776320, 2023). "To verify RIOX2 upregulation at the protein level, we conducted an immunohistochemical assay using a prostate cancer tissue array containing 40 cases." (PMID 36776320, 2023). "Similar results were also observed from the MSKCC dataset; RIOX2 mRNA levels were significantly higher in prostate cancers with genetic gain." (PMID 36776320, 2023). "To determine if RIOX2 expression was directly regulated by the androgen/AR signal pathway, we analyzed RIOX2 expression in prostate cancer LNCaP cells after androgen stimulation." (PMID 36776320, 2023). "COX regression analysis with multiple variates, including clinicopathological factors, revealed that only RIOX2 upregulation was significantly correlated with disease-specific survival in prostate cancer patients." (PMID 36776320, 2023). "RIOX2 gene was initially reported as a c-Myc downstream target involved in cell proliferation, and c-Myc is a proven oncogene in prostate cancer." (PMID 36776320, 2023). "We conducted a Spearman correlation analysis and found that RIOX2 expression was strongly correlated with ZNF143 expression while moderately with IKZF1 expression in prostate cancers." (PMID 36776320, 2023). "Further analysis discovered that RIOX2 expression was correlated with its promoter hypomethylation in prostate cancers, indicating an epigenetic mechanism involved in RIOX2 upregulation." (PMID 36776320, 2023). "Deceased patients due to prostate cancer also showed a significantly higher level of RIOX2 mRNA levels compared to alive patients." (PMID 36776320, 2023). "In addition, RIOX2 mRNA levels were strongly correlated with the fraction value of genomic alterations in prostate cancers." (PMID 36776320, 2023). "Interestingly, among these Myc family members, only c-Myc was significantly upregulated in prostate cancers compared to benign compartments, suggesting that c-Myc is potentially a major regulator of RIOX2 expression in prostate cancer." (PMID 36776320, 2023). "However, ZNF143 expression was not significantly altered in prostate cancer tissues, indicating it is unlikely a causative factor of RIOX2 upregulation in prostate cancer." (PMID 36776320, 2023). "Consistently, RIOX2 mRNA expression was observed in all prostate cancer cell lines with or without AR expression." (PMID 36776320, 2023). "Other six genes, including upregulated JARID2, JMJD4, and RIOX2, as well as downregulated HIF1AN, HR, and UTY were not reported in prostate cancers so far." (PMID 36776320, 2023).
cancer (22 papers, 2014 to 2025). A tumor composed of atypical neoplastic, often pleomorphic cells that invade other tissues. "As an oncogene, ribosomal oxygenase 2 (RIOX2) has been associated with a variety of cancers." (PMID 34855761, 2021). "Our results showed that RIOX2 promoter methylation was significantly lower in cancer tissues compared to benign tissues." (PMID 36776320, 2023). "Its expression is upregulated in several cancers, including lung and breast cancer, and knockdown of RIOX2 in A549 cells inhibited cell proliferation." (PMID 29914368, 2018). "Both, human RIOX1 and RIOX2 have been described to be involved in cancer cell growth." (PMID 29914368, 2018).
RIOX2 also shares sentences with these, for which no sentence is quoted: tumor (16 papers); glioblastoma (8); breast carcinoma (5); gastric cancer (5); lymph node metastasis (5); colon cancer (4); hepatocellular carcinoma (4); lymphoma (4); cholangiocarcinoma (3); brain tumor (2); esophageal cancer (2); gastric tumor (2); leukemia (2); lung squamous cell carcinoma (2); neuroblastoma (2); promyelocytic leukemia (2); acute lymphoblastic leukemia (1); adenocarcinoma (1); adrenal cortex carcinoma (1); bladder urothelial carcinoma (1); breast invasive carcinoma (1); colon adenocarcinoma (1); colorectal cancer (1); COVID-19 (1); esophageal squamous cell carcinoma (1); glioma (1); head and neck squamous cell carcinoma (1); hepatitis B virus infection (1); kidney cancer (1); lung diseases (1).
A further 16 diseases each share a sentence with RIOX2 in 1 paper.